GPX4 (glutathione peroxidase 4)
Diseases named in the same sentence as GPX4 in open-access papers (continued):
Sharing a sentence is not in itself a finding about the gene and the disease.
infection (70 papers, 2016 to 2026). The state of being infected such as from the introduction of a foreign agent such as serum, vaccine, antigenic substance or organism. "Although HCMV-infected cells are marginally more susceptible to cell death induced by RSL3-mediated GPX4 inhibition at 48 hpi, in all of the assays we performed, infected cells became less susceptible to ferroptotic cell death as infection progressed." (PMID 39772623, 2025). "Studies have indicated that GPX4 was implicated in the infection by certain microorganisms, such as Mycobacterium tuberculosis." (PMID 41142608, 2025). "First, dysregulation of the Nrf2/GPX4 signaling axis is a hallmark event in infections caused by multiple pathogens." (PMID 41479924, 2025). "Subsequently, GPX4 knockout mice were found to aggravate TB infection, while overexpression of GPX4 significantly reduced bacterial load and risk of infection." (PMID 38562175, 2024). "Previous studies have demonstrated that GPX4 deficiency in mice leads to increased susceptibility to infection with Mycobacterium tuberculosis, as evidenced by increased lung necrosis and bacterial burden." (PMID 37956169, 2023). "Thus, the enhanced host cell ferroptosis caused by RSL3-mediated reduction in GPX4 prior to infection is likely to be the reason for the increased parasite propagation." (PMID 40667873, 2025). "Infection of GPX4-deficient mice with Leishmania could lead to a reduction in the number of CD4+ T cells, which contributes to the maintenance of Leishmania in vivo." (PMID 36160441, 2022). "Western blotting analysis revealed that PPRV infection suppressed the expression of GPX4 and FTMT in mitochondrial fractions at 24 and 48 h and in a dose-dependent manner at 48 h." (PMID 40197059, 2025). "Western blot analysis showed that compared with naive BMDMs, BLP‐trained BMDMs exhibited significantly increased GSS, GCLM, and GPX4 both before infection and 1–6 h after infection." (PMID 41117166, 2025). "The findings revealed that the expression level of the T. gondii B1 gene in Vero cells overexpressing GPX4 was significantly lower compared to control cells at 6, 24, and 48 h post-infection." (PMID 40422259, 2025). "Following the inhibition of GPX4 expression, membrane lipid peroxides accumulated continuously in T cells post-infection, leading to a decrease in cell viability." (PMID 40422259, 2025). "Our results elucidate the pathogenic mechanisms of T. gondii and highlight the pivotal role of GPX4 in regulating infection and proliferation." (PMID 40422259, 2025). "We previously showed that GPX4 protein expression decreased considerably by 24 hpi and have now expanded on these findings to show that GPX4 levels remain low throughout infection." (PMID 39772623, 2025). "In animal experiments, GPX4 expression levels were also downregulated by SC1401 infection, and these alterations were highly correlated with ferroptosis." (PMID 40281583, 2025). "WB data revealed that the protein expression of GPX4 was significantly decreased at 24 and 72 h post-infection." (PMID 40422259, 2025). "RT-qPCR analysis revealed that, except at 12 h post-infection, the mRNA expression of GPX4 in brain tissue from RH strain-infected mice was significantly reduced." (PMID 40422259, 2025). "Molecular analyses revealed infection-induced downregulation of ferroptosis suppressor GPX4 and upregulation of pro-ferroptotic ACSL4 in macrophages and mice." (PMID 40667873, 2025). "Leishmania infection in GPX4-deficient mice leads to a reduction in the number of CD4+ T cells, which contributes to the establishment of infection." (PMID 40667873, 2025). "The results indicated a significant reduction in the mRNA expression level of GPX4 following infection with T. gondii." (PMID 40422259, 2025). "GPX4 expression returned to close to pre-infection levels at 96 hpi with acyclovir treatment, likely because inhibition of viral replication allowed GPX4 expression to return to normal." (PMID 39772623, 2025).
infection (continued). "Following transduction with sh-GPX4 clone 1, GPX4 knockdown was mild, allowing infection and virus production to proceed similarly to control shGFP-expressing cells." (PMID 39772623, 2025). "HCMV-infected cells became less sensitive to GPX4 inhibition as infection progressed, requiring substantially higher levels of GPX4 inhibitors to induce ferroptosis compared to uninfected cells." (PMID 39772623, 2025). "The results show that the expression levels of il-1β and tnf-α were significantly reduced in cells overexpressing gpx4 prior to infection with A. hydrophila." (PMID 40699725, 2025). "In contrast, during the late phase of infection, the pathogen inhibits the classical GPX4-glutathione (GSH) axis, facilitating ferroptosis and allowing bacterial egress from host cells." (PMID 41212588, 2025). "Subsequently, the protein levels of xCT and GPX4 began to significantly decrease 4 h to 8 h post-infection, and the content of GSH also decreased accordingly." (PMID 41343264, 2025). "For example, HIV promotes ferroptosis by suppressing GPX4 in T cells during the early stages of infection, which is critical for HIV pathogenesis." (PMID 40667873, 2025). "Continuous expression of NRF2 and GPX4 proteins was detected, with their expression gradually decreasing as the time of infection increased." (PMID 41356483, 2025). "Glutathione peroxidase 4 (GPX4) plays a crucial role in regulating lipid peroxidation and is associated with infection and inflammation, particularly in terms of its effects on inflammatory cytokines and ferroptosis." (PMID 40699725, 2025). "In mouse mammary gland tissue infection induced by K. pneumoniae, pre-treatment with C-EVs, M-EVs or CM-EVs augmented Nrf2/GPX4 and ZO-1/Occludin expression, diminished by K. pneumoniae infection." (PMID 39953606, 2025). "We measured viral titers, virus spread following low MOI infection, and levels of lipid peroxidation in the cells expressing the empty vector or GPX4-expressing vector." (PMID 39772623, 2025). "To investigate the potential for viral transcriptional regulation of GPX4, we examined mRNA levels for GPX4 and found that GPX4 expression is decreased throughout infection by ~50%." (PMID 39772623, 2025). "Infection with SC1401 significantly decreased the expression level of GPX4, whereas infection with SC1401Δcdt at an MOI of 100 significantly increased the expression of GPX4 compared with that in SC1401-infected cells." (PMID 40281583, 2025). "Our data showed that both biotypes of BVDV infection suppressed the expression of Nrf2, SLC7A11, and GPX4 in MDBK cells compared to mock-infected cells in a post infection time-dependent manner." (PMID 38226812, 2024). "The mRNA transcription level of antioxidant downstream genes Glutathione Peroxidase 4 (GPX4) decreased (p < 0.01) after DK/212 infection." (PMID 38542289, 2024). "At the late stage of infection (20 dpi), our results demonstrated that GPX4-OE markedly attenuated the accumulation of lipid peroxidation." (PMID 39654902, 2024). "It was reported that the lethal lipid peroxides (LPOs) quickly accumulated in the membrane of T cells depleted of GPX4 which will subsequently undergo ferroptosis and lack the capability to expand and protect the cells from infection in vivo." (PMID 36926345, 2023). "Clinical studies have shown that infection with SARS-CoV-2 leads to GSH deficiency and GPX4 inhibition in the body." (PMID 37303950, 2023). "Using conditional knockout mice as well as in vitro infection experiments, we reveal that Gpx4 expression by myeloid cells plays a central role in determining these outcomes." (PMID 36069923, 2022). "To confirm and extend our observations in TB patients, we also evaluated GPX4 protein expression in lung tissue sections previously obtained from rhesus macaques at 16 wk post-infection (p.i.)with the virulent H37Rv-mCherry Mtb strain." (PMID 36069923, 2022).
infection (continued). "Consistently, the Nrf2/HO-1 and ferritin/NCOA-4 axes (controlling iron release) and GPX4 expression level all recovered at 24 h post-infection." (PMID 35265210, 2022). "Molecular analysis further demonstrated that the infection of BCG significantly inhibited the expression of Gpx4 and Fsp1 proteins, but increased HO-1 expression." (PMID 36211962, 2022). "T cell survival and proliferation are also suggested to be regulated by ferroptosis, as a GPX4-deficient T cell model showed that GPX4 was required for CD4+ T cell and CD8+ T cell proliferation during infection." (PMID 35563704, 2022). "We reasoned that the increased GPX4 expression due to BoHV-1 infection would be beneficial for preventing the ferroptotic cell death to facilitate viral productive infection, which needs further study in the future." (PMID 31011285, 2019). "Furthermore, the mRNA and protein expression levels of GPX4 in Vero cells were significantly diminished following infection with the RH strain of T. gondii." (PMID 40422259, 2025). "Similarly, during bovine viral diarrhea virus (BVDV, family Flaviviridae) infection, the virus downregulates cytosolic and mitochondrial GPX4 via the Nrf2/GPX4 pathway, leading to lethal lipid peroxidation and promoting cellular ferroptosis." (PMID 41356483, 2025). "The concurrent downregulation of GPX4 and increase in lipid peroxidation during infection suggests that HCMV-infected cells may be sensitized to ferroptosis." (PMID 39772623, 2025). "Conversely, the infection led to a decrease in the protein level of GPX4." (PMID 40667873, 2025). "Additionally, except at 6 h and 12 h post-infection, the mRNA expression of GPX4 in brain tissue from RH strain-infected mice was significantly reduced." (PMID 40422259, 2025). "Se treatment decreased the transcriptional activity of GPX4 after infection." (PMID 41157575, 2025). "However, restoring the ATF4 level via Ad-ATF4 infection led to decreased levels of GPX4 and phosphorylated mTOR, S6, and 4EBP1 by erastin, suggesting that ATF4 mediates the erastin-induced mTOR inhibition and the subsequent activation of ferroptosis signaling." (PMID 40227255, 2025). "Further studies demonstrated that the mRNA and protein expression levels of GPX4, a key regulator of ferroptosis, were significantly downregulated in the brain and liver tissues of mice following infection, while the parasitic load of T. gondii was concurrently increased." (PMID 40422259, 2025). "Therefore, GPX4 plays a crucial role in inhibiting pathogen infection and holds potential value as an infection marker." (PMID 40264754, 2025). "However, the expression of GPX4 was significantly suppressed at 48- and 72-h post-infection, which was consistent with the results of the LDH release assay." (PMID 38790682, 2024). "The results demonstrated that Brucella M5 could induce ferroptosis of macrophages by inhibiting the GPX4-GSH axis at the late stage of infection but mitigated ferroptosis by up-regulating the GCH1-BH4 axis at the early infection stage." (PMID 38790682, 2024). "Similarly, our present results showed that Brucella M5 induced macrophage ferroptosis at the late stage of infection by suppressing the GPX4-GSH pathway." (PMID 38790682, 2024). "The results showed that, compared to the control group, the down-regulation of antioxidant gene mRNA caused by DK/212 infection was inhibited after interference with the expression of the TRIM21 gene, and the protein level of NRF2, SLC7A11, and GPX4 was increased." (PMID 38542289, 2024). "Our results showed that TgCtwh3 infection impaired the cystine/GSH/GPx4 axis, an effect that could be relieved by DFP." (PMID 37651502, 2023). "Thus, our data showing significant suppression of GPX4 expression during fatal IOE infection suggest that virulent IOE evade host’s antioxidant and anti-bacterial response and likely cause liver damage by inhibiting the expression of GPX4." (PMID 37956169, 2023).
infection (continued). "HSV-1 also depletes the cellular antioxidant glutathione peroxidase 4 (GPX4) during infection." (PMID 36902102, 2023). "T cell lipid peroxidation induces ferroptosis and reduces immunity to infection, and Gpx4 is critical for the homeostatic survival of CD8 T cells and the expansion of CD4+ and CD8+ T cells in response to infection by preventing membrane lipid peroxidation and ferroptosis upon TCR triggering." (PMID 35990689, 2022). "Meanwhile, GPx4 decreased after infection, and DFP could restore it to normal levels." (PMID 37651502, 2023). "Infection of ZIKV progressively damaged mouse testes, increased testicular oxidative stress as indicated by the levels of reactive oxygen species, nitric oxide, glutathione peroxidase 4, spermatogenesis-associated-18 homolog in sperm and pro-inflammatory cytokines including IL-1β, IL-6, and G-CSF." (PMID 29447264, 2018). "Treatment with RSL3 reduced virus titers in a high MOI infection by greater than sixfold relative to dimethyl sulfoxide (DMSO) vehicle treatment in each experiment, indicating a role for GPX4 in infection." (PMID 39772623, 2025). "Western blotting for FTH and GPX4 in lung tissues revealed that FTH was significantly increased and that GPX4 was significantly decreased by SC1401 infection." (PMID 40281583, 2025). "Western blotting analysis revealed that PPRV infection suppressed the expression of SLC7A11 and GPX4, while increasing ACSL4 expression in EECs in a dose- and time-dependent manner." (PMID 40197059, 2025). "The knockdown of HSP90 significantly increased the GPX4 expression levels, decreased CHAC1 mRNA levels, and reduced intracellular iron content post-ETEC infection, suggesting that the reduction in HSP90 blocked the occurrence of ferroptosis." (PMID 40867813, 2025). "The role of Gpx4 is vital for the survival of CD8+ T cells, as well as the proliferation of CD4+ and CD8+ T cells during infection." (PMID 40070882, 2025). "The L8824 cell line served as a convenient model for probing gpx4 functionality in M. amblycephala, although we acknowledge that interspecies disparities between grass carp and blunt snout bream could subtly alter cellular responses to infection or ferroptotic stimuli." (PMID 40699725, 2025). "Conversely, the expression of solute carrier family members SLC7A11, glutathione peroxidase 4 (GPX4), and the iron efflux pump protein FPN1/SLC40A1 was downregulated, with this effect alleviated in the TbΔirp2 infection group." (PMID 40034497, 2025). "To examine the role of GPX4 in infection, we titrated HCMV-infected cells with two compounds that target the GPX4 pathway at different points." (PMID 39772623, 2025). "Pathogen infection or viral proteins induce the release of inflammatory cytokines such as IL-6 and TNF-α, which subsequently suppress key antioxidant proteins like GPX4 and SLC7A11, initiating ferroptosis." (PMID 41479924, 2025). "PM10 exposure followed by infection significantly increased the protein levels of TNF-α (A), IL-1β (B), and CXCL2 (C), and decreased GPX4 (D) and Nrf2 (E) (p < 0.001 for each)." (PMID 38928968, 2024). "As a general trend, we observed a slight decrease in the expression of GPX1, GPX4, SELENOO and SELENOS at days 2, 3 or 4 post-infection." (PMID 35163318, 2022). "As a proof of concept, we introduced two single-guide RNAs (sgRNAs) targeting the gene glutathione peroxidase 4 (GPX4) by lentiviral transduction into a pool of 50 cell lines, and performed scRNA-seq at either 72 or 96 h post-infection (“Methods”)." (PMID 32855387, 2020). "albicans infection induced ferroptosis in vaginal tissues and macrophages, as manifested by lipid ROS accumulation, Fe2+ overload, GSH depletion, downregulation of GPX4 and SLC7A11, upregulation of ACSL4, 4-HNE, and MDA, and mitochondrial structural damage." (PMID 42072050, 2026).
infection (continued). "In the early stages of infection (Burkitt-like hyperproliferation phase), EBV induces lipid metabolism and ROS production, making B cells dependent on cystine import mediated by SLC7A11 and the activity of Gpx4 to resist ferroptosis." (PMID 40170865, 2025). "GPX4 and TXNRD1, selenoprotein antioxidant genes responsible for maintaining cellular homeostasis and protection against oxidative stress and hydroperoxides, demonstrated limited modulation after infection." (PMID 41157575, 2025). "Our findings revealed that after PbA infection, ACSL4 expression increased in splenocytes, while SLC7A11 and GPX4 expressions significantly decreased, indicating that malaria infection leads to iron homeostasis imbalance and elevated lipid peroxidation in the host." (PMID 41422632, 2025). "This revealed that M5 inhibited ferroptosis via the GCH1/BH4 pathway in the early stage of infection, promoting its intracellular proliferation, but induced ferroptosis through the GPX4/GSH pathway to facilitate its escape and spread in the late stage of infection." (PMID 40606156, 2025). "Notably, GPX4 inhibitor RSL3 exhibited context-dependent effects: pre-infection treatment enhanced replication, while post-infection administration inhibited growth." (PMID 40667873, 2025). "Notably, the mRNA expression of GPX4 in both brain and liver tissues of PRU strain-infected mice was significantly decreased at 7, 14, and 21 days post-infection." (PMID 40422259, 2025). "To further explore whether AMPK regulates BECN1 and other molecules, such as ACSL4 or GPX4, in the context of CAP-induced ferroptosis, we constructed a stable cell line with AMPK knockdown through lentivirus-mediated shRNA infection." (PMID 40438695, 2025). "We used a set of GPX4-OE retroviruses to overexpress each of three GPX4 isoforms (cGPX4, mGPX4, or nGPX4) in P14 cells, and those transduced P14 cells (mAm+) were transferred separately into recipient mice, followed by LCMV Cl13 infection." (PMID 39654902, 2024). "It was reported that the deletion of glutathione peroxidase 4 (GPX4), an intracellular glutathione peroxidase crucial for preventing lipid peroxidation, led to compromised clonal expansion of CD8+ T cell during acute-resolved infections." (PMID 39654902, 2024). "Compared to uninfected mice, EM infection did not change the expression level of total GPX4 in liver tissues." (PMID 37956169, 2023). "It is reported that T cells with GPX4 deficiency undergo ferroptosis and negatively affect their anti-virus or anti-infection function, and the ferroptosis is inhibited in GPX4 or FSP1 overexpressed T cells without affecting their effector function." (PMID 36926345, 2023). "The infection of BCG is comparable to intracellular ROS production and cell peroxidation, and to the inhibition of the expression of Gpx4 and Fsp1 with that of 0.2 mM of H2O2, although the effect was to a lesser extent compared to that of 2.0 mM RSL in RAW264.7 cells." (PMID 36211962, 2022). "Interestingly, while GPX4 overexpression was accompanied by a slight decrease in basal levels of lipid peroxidation in uninfected cells, there was no significant reduction in lipid peroxidation in GPX4-expressing cells during infection." (PMID 39772623, 2025). "GPX4 overexpression did not affect virus production in a high MOI infection." (PMID 39772623, 2025). "Consistent with a previous report that E. coli inhibited SLC7A11/GPX4 signalling in BMECs, infection with E. coli resulted in the inhibition of SLC7A11 and GPX4 expression in endometrial tissue and BEECs, which may be responsible for the imbalance in redox homeostasis in this study." (PMID 41413615, 2025). "The expression profiles of key Nrf2 pathway components, including Nrf2, xCT, and GPX4, were decreased at both the transcript (NFE2L2, p = 0.009681, xCT, p = 0.000055, and GPX4, p = 0.040776) and protein levels (p < 0.05 or p < 0.01) in the infection group compared to the control group." (PMID 41343264, 2025).